FANCC (FA complementation group C)
Description:
DNA repair protein that may operate in a postreplication repair or a cell cycle checkpoint function. May be implicated in interstrand DNA cross-link repair and in the maintenance of normal chromosome stability. Upon IFNG induction, may facilitate STAT1 activation by recruiting STAT1 to IFNGR1.
Synonyms: FAC; FACC; FA3; LOC105376156
Tractability: PROTAC: ubiquitination databases record sites on it.
Gene: Protein-coding gene on chromosome 9 (95,099,054 to 95,426,796, reverse strand). Ensembl gene ENSG00000158169.
Subcellular location: Nucleus; Cytoplasm
Subcellular location (Human Protein Atlas): Nucleoplasm
Pathways (Reactome):
DNA Repair: Fanconi Anemia Pathway
Immune System: PKR-mediated signaling
Gene Ontology:
Molecular function: protein binding
Biological process: cellular response to oxidative stress; DNA repair; interstrand cross-link repair; nucleotide-excision repair; protein-containing complex assembly
Cellular component: chromatin; cytosol; Fanconi anaemia nuclear complex; nucleoplasm; cytoplasm; nucleus
Genetic constraint (gnomAD): Loss-of-function variants: 50 observed, 61.9 expected, observed/expected ratio (o/e) 0.81, 90% interval 0.64 to 1.02. The upper end of that interval is the gene's LOEUF score, 1.02, which puts it in group 4 of 6, group 1 being the genes least tolerant of losing a copy. Missense variants: 597 observed, 625.24 expected, observed/expected ratio (o/e) 0.95, 90% interval 0.89 to 1.02. Synonymous variants: 252 observed, 232.94 expected, observed/expected ratio (o/e) 1.08, 90% interval 0.98 to 1.2.
Gene-disease validity (ClinGen):
ClinGen rates the evidence that FANCC causes each of these diseases.
Fanconi anemia complementation group C (autosomal recessive): Definitive.
Homologues: Orthologues: chimpanzee FANCC (99% identical), macaque FANCC (93% identical), dog FANCC (76% identical), pig FANCC (75% identical), guinea pig FANCC (74% identical), rabbit FANCC (71% identical), mouse Fancc (68% identical), rat Fancc (67% identical), tropical clawed frog fancc (39% identical), zebrafish fancc (29% identical).
Diseases named in the same sentence as FANCC in open-access papers:
FANCC is named in the same sentence as 87 diseases in open-access papers, as found by Europe PMC text mining. Sharing a sentence is not in itself a finding about the gene and the disease. The quoted sentences say what the papers report.
Fanconi anemia (62 papers, 2010 to 2026). Fanconi anemia (FA) is a hereditary DNA repair disorder characterized by progressive pancytopenia with bone marrow failure, variable congenital malformations and predisposition to develop hematological or solid tumors. "The monoallelic germline alterations in FANCA and FANCC reflect carrier status only; biallelic alterations in these genes are associated with the autosomal recessive condition of Fanconi anemia." (PMID 36611031, 2023). "Three variants in immune genes were categorized in ClinVar as (L)P in association with the AR inheritance mode for Fanconi anemia, complementation group C (FANCC), primary ciliary dyskinesis 7 (DNAH11), and primary ciliary dyskinesis 28 (SPAG1)." (PMID 35877578, 2022). "The Fanconi Anemia Group C complementation group gene (FANCC) encodes a protein, FANCC, which plays an indispensable role in the pathogenesis of Fanconi Anemia." (PMID 35659106, 2022). "Of note, these variants were associated with recessive inheritance for Fanconi anemia, complementation group C (FANCC), primary ciliary dyskinesis 7 (DNAH11), and primary ciliary dyskinesis 28 (SPAG1) so far." (PMID 35877578, 2022). "FANCC, which belongs to the Fanconi anemia complementation group, has been reported as a susceptibility gene for BC." (PMID 34926254, 2021). "It is reported that numerous human genetic diseases were caused by single nucleotide mutation, such as the 878 G > A (AVPR2 W293X) in X-linked Nephrogenic diabetes insipidus and the 1517 G > A (FANCC W506X) in Fanconi anemia." (PMID 31057603, 2019). "Mutations in Fanconi complementation group C (FANCC) is associated with the development of Fanconi anemia (FA), an autosomal recessive disease characterized by developmental abnormalities, chromosomal instability and cancer susceptibility." (PMID 31484545, 2019). "FANCC is also linked to Fanconi anemia that has a phenotype including craniosynostosis, microencephaly and small eyes." (PMID 30631343, 2018). "Mutations in the FANCC gene lead to Fanconi anemia, a genetic disease characterized by a progressive depletion of bone marrow cells." (PMID 24676280, 2014). "TZFP has also been linked to the Fanconi Anemia pathway due to its ability to bind to the FA factor FANCC." (PMID 23634227, 2013). "The biological knowledge-based binning approach identified rare variants in FANCC (Fanconi anemia complementation group C) as well as 7 evolutionary conserved regions significantly associated with a LOAD-related neuroimaging endophenotype, entorhinal cortex thickness." (PMID 28539126, 2017). "Of the 19 patients diagnosed with Fanconi anemia, the majority of mutations were found in the FANCA gene (n = 12), followed by FANCG (n = 4) and FANCC (n = 3)." (PMID 41520327, 2026). "In this study, Fanconi anemia was genetically confirmed in 19 individuals, with the majority of pathogenic or likely pathogenic variants identified in the FANCA, FANCG, and FANCC genes." (PMID 41520327, 2026). "Fanconi anemia complementation group C (FANCC), a member of the Fanconi anemia gene family, exerts a protective role by facilitating mitophagy in immune processes." (PMID 40213654, 2025). "miR-24-1 upregulated the expression of its adjacent genes fructose-1,6-bisphosphatase 1 (FBP1) and Fanconi anemia, complementation group C (FANCC) in HEK293T cells." (PMID 37176056, 2023). "Another interesting finding in our cohort is the high incidence of monoallelic variants in other Fanconi anemia (FA) genes: FANCA, FANCC, FANCD2, RAD51C, FANCG and FANCI." (PMID 36290365, 2022). "Within the 12 families, three variants were found in FANCC and FA complementation group M (FANCM) that were associated with Fanconi anemia and spermatogenic failure, respectively." (PMID 35877578, 2022).
Fanconi anemia (continued). "BRIP1 and FANCC belong to the Fanconi anemia pathway while MDC1 and TP53BP1 are conserved DNA damage response genes." (PMID 34220964, 2021). "The second most commonly altered gene, FANCC, is a critical component of the Fanconi anemia core complex." (PMID 34440225, 2021). "Among these, there were FHIT, WWOX, FANCC (belonging to the Fanconi anaemia pathway), CADM1, and IMMP2L." (PMID 34187875, 2021). "The three Fanconi anemia genes FANCC, FANCF, and FANCL were identified as candidate autophagy factors via whole genome screening." (PMID 33575215, 2020). "Recently, the detection of pathogenic variants in Fanconi anemia DNA damage repair pathway genes, such as BRCA2, BRIP1, FANCC, and FANCE was also reported in familial CRCs34." (PMID 30850667, 2019). "Tumor 2 had bi-allelic chromosome 9q deletions of PTCH1 and FANCC (Fanconi anemia complementation group C)." (PMID 31362756, 2019). "Most fanconi anemia patients harbour homozygous or double heterozygous mutations in the FANCA (60-65%), FANCC (10-15%), FANCG (~10%) or FANCD2 (3-6%) genes." (PMID 29400309, 2018). "FANCC (fanconi anemia complementation group C) has been shown to modulate TLR and p38 MAPK-dependent expression of IL-1β in macrophages." (PMID 28539126, 2017). "The Fanconi anemia group C protein (FANCC) is one of the several proteins that comprise the Fanconi anemia (FA) network involved in genomic surveillance." (PMID 24676280, 2014). "TZFP makes a heterodimer with the FA group C protein (FANCC), which is one of at least 13 distinct complementation proteins involved in the autosomal recessive disorder Fanconi anemia (FA)." (PMID 23634227, 2013). "Our analysis identified families with heterozygous, deleterious mutations in the DNA repair genes FANCC and BLM, which are responsible for the autosomal recessive disorders Fanconi Anemia and Bloom syndrome." (PMID 23028338, 2012). "FANCC is part of the Fanconi anemia core complex, which has been shown to promote HR." (PMID 39485057, 2024). "In our study, moderately increased BC risk was defined for mutations in the Fanconi anemia genes FANCC (OR = 2.4) and FANCI (OR = 4.3), but not for FANCM (OR = 0.6), although the difference was not significant." (PMID 39684352, 2024). "Homozygous or compound heterozygous PVs in FANCC and ERCC5 are known to be linked to autosomal recessive disorders, Fanconi anemia complementation group C (MIM: 227645) and Xeroderma pigmentosum complementation group G (MIM: 278780), respectively, known to exhibit increased risk to cancer." (PMID 36969007, 2023). "Moreover, mice lacking the cytosolic Cu/Zn superoxide dismutase 1 (Sod1) and the Fanconi Anaemia DNA repair pathway gene FancC develop hematopoietic failure and liver steatosis." (PMID 35136057, 2022). "The second most commonly altered genes were FANCC (2/6; 33%) which is a critical component of the Fanconi anemia core complex, and NOTCH2 (2/6; 33%), which is a key part of the Notch signaling pathway that controls the normal morphological development of multicellular organisms." (PMID 34440225, 2021). "Here, we show that SMC5 dysfunction in avian DT40 B cells causes mitotic delay and hypersensitivity toward DNA intra‐ and inter‐strand crosslinkers (ICLs), with smc5 mutants being epistatic to FANCC and FANCM mutations affecting the Fanconi anemia (FA) pathway." (PMID 31867888, 2020).
Fanconi anemia (continued). "The FANCC gene is a DDR-related gene in the Fanconi anemia pathway." (PMID 32793315, 2020). "Finally, FANCC belongs to the Fanconi anaemia DNA repair pathway, which has been proposed to play a role in inherited predisposition to CRC." (PMID 31366136, 2019). "Among DNA repair genes, we detected a high presence of members of the Fanconi Anemia Complementation Group (FANCC, FANCD2, FANCG, FANCA, and FANCE), which participate in homologous recombination DNA repair, and genes involved in double-strand break repair (BRCA2, BRIP1, BARD, BLM, CHEK2, and PALB2)." (PMID 30487452, 2018). "FANCC depletion diminished the nuclear foci formation of FANCD2 upon MMC exposure, indicating a defect in the DNA damage response of the Fanconi anemia core complex." (PMID 41065314, 2025). "In CRC, significant associations of HR (BRCA1, BRCA2, BARD1, PALB2 and BRIP1) and Fanconi anaemia (FANCA, FANCC and FANCG) genes with TMB were identified." (PMID 37821580, 2023). "Deleterious alterations were also identified in nearly all (13/14) tumours in members of the Fanconi anaemia complementation groups, including FANCD2, FANCF, FANCC, FANCA, and FANCE." (PMID 34045664, 2022). "HRR alterations involve Fanconi anemia genes (PALB2, FANCA, FANCL, FANCI, FANCC), core RAD genes (RAD50, RAD51, RAD51B, RAD51C) as well as DNA damage response genes (ATM, ATR, CHEK1, CHEK2)." (PMID 36531003, 2022). "Whereas, the binding of FANCC requires FANCA/FANCG binding and the products of other Fanconi Anemia genes." (PMID 25953249, 2015). "To determine the feasibility of in vivo BM stem cell gene transfer as a means to correct the Fanconi anemia stem cell defect, we first designed an HIV-derived LV coding for the murine FancC transgene in fusion with the EGFP reporter protein." (PMID 20885913, 2010). "Other common genetic etiologies associated with EA/TEF include chromosomal disorders (trisomy 21, trisomy 18, trisomy 13), Feingold syndrome (MYCN), Fanconi anemia (multiple genes including FANCB, FANCC, FANCG, BRIP1) and other recurrent deletion and duplication syndromes." (PMID 36909054, 2023). "In addition, the top two enriched KEGG pathways were: 1) the Fanconi Anaemia pathway (represented by ATR, BRIP1, ERCC4, FANCC and POLH) and the FoxO signalling pathway (represented by CREBBP, NLK, PRKAA2, PRKAB1, PTEN and STK11)." (PMID 35768547, 2022). "Interestingly, more than half of the possible pathogenic variants identified in patients with mesothelioma were located within genes of the Fanconi anemia pathway (FANCA, FANCC, FANCD2, and FANCM)." (PMID 31263571, 2019). "Additionally, we found 7 monoallelic pathogenic variants (2%, 7/327) in 6 genes (besides BRCA1/2) of the interstrand crosslink DNA repair Fanconi anemia pathway (FANCB, FANCC, FANCF, FANCI, FANCL, FANCM) and 1 in RAD51C, a Fanconi-like phenotype gene." (PMID 30262796, 2018). "Three members of the Fanconi Anemia pathway (FANCB, FANCC, and FANCL) were also down regulated." (PMID 24098381, 2013).
breast carcinoma (22 papers, 2008 to 2025). "A previous study on actionable mutations in various non-BRCA cancer-associated genes found deletions in similar regions of the FANCC gene (c.355_360delTCTCATinsA) in Black/African American women with a familial history of breast cancer." (PMID 41296379, 2025). "Mutations in the FANCC gene have been associated with an increased risk of developing breast cancer yet they seem to be rare compared to mutations in other DNA repair genes." (PMID 38313678, 2024). "The pathogenic variant c.455dup in the FANCC gene was found in a patient with Hodgkin lymphoma and breast cancer." (PMID 39684352, 2024). "The heterozygous variant FANCC, c.1642C > T, p.R548* is discussed as a low penetrance risk allele for breast cancer." (PMID 35877578, 2022). "After FA was stratified into subsets defined by complementation assays, an increased risk of breast cancer was attributed to heterozygous carriers of FANCC mutations." (PMID 31467304, 2019). "Our study provided evidence, for the first time, that the FANCC deleterious mutation exists in Chinese familial breast cancer patients, with a frequency of 0.4% in our cohort." (PMID 30967997, 2019). "We used the Oncoarray project to genotype two truncating FANCC variants (p.R185X and p.R548X) in 64,760 breast cancer cases and 49,793 controls of European descent." (PMID 31467304, 2019). "In the present study, we genotyped two truncating variants of FANCC (p.R185X and p.R548X) using the Oncoarray in 64,760 female breast cancer cases and 49,793 female population controls of European descent." (PMID 31467304, 2019). "The gene for FA type C, FANCC, has been proposed as a breast cancer susceptibility gene based on epidemiological and sequencing studies." (PMID 31467304, 2019). "If this applies to all truncating variants in FANCC it would suggest there are differences between FA genes in their roles on breast cancer risk and demonstrates the merit of large consortia for clarifying risk associations of rare variants." (PMID 31467304, 2019). "We conclude that the breast cancer risk association of these two FANCC variants, if any, is much smaller than for BRCA1, BRCA2 or PALB2 mutations." (PMID 31467304, 2019). "The germline mutations of 98 genes including 24 known and candidate breast cancer susceptibility genes were screened by a gene panel sequencing assay, and no pathogenic or likely pathogenic mutation was found except FANCC c.339G>A." (PMID 30967997, 2019). "Epidemiological and segregation studies have provided some evidence of an increased breast cancer risk for grandmothers of FA patients, particularly those who carry the FANCC mutation." (PMID 31467304, 2019). "While molecular studies investigating cancer risk in heterozygotes have mostly been inconclusive, a recent molecular study of 944 relatives of FA probands did suggest an increased risk of breast cancer in FANCC mutation carriers." (PMID 18786261, 2008). "This suggests a predisposing role for FANCC variants in breast cancer." (PMID 41296379, 2025). "Another three truncating mutations in FANCC were observed in 438 breast cancer families, while 1 pathogenic mutation was identified in an additional 957 breast cancer families; no deleterious mutation was reported in 464 healthy controls nor in 1,000 genomic data." (PMID 32300589, 2020). "We aimed to identify the germline mutations of FANCC in high-risk breast cancer patients in China." (PMID 30967997, 2019). "Therefore, we aimed at, for the first time in mainland China, assessing the germline mutation of FANCC in high-risk breast cancer patients in women from eastern China, by screening the complete coding regions and exon-intron boundaries of FANCC." (PMID 30967997, 2019).